Y_RNA (Y RNA )
Gene: Miscellaneous RNA gene on chromosome 12 (93,021,606 to 93,021,712, forward strand). Ensembl gene ENSG00000207365.
Homologues: Orthologues: chimpanzee Y_RNA (94% identical), macaque Y_RNA (93% identical). Paralogues in human: RNY1 (79% identical), Y_RNA (79% identical), Y_RNA (78% identical), RNY1P11 (77% identical), Y_RNA (77% identical), RNY1P5 (76% identical), Y_RNA (76% identical), Y_RNA (75% identical), RNY1P8 (74% identical), Y_RNA (74% identical), RNY1P2 (73% identical), RNY1P7 (73% identical), and 91 more.